SOX17 (SRY-box transcription factor 17)
Diseases named in the same sentence as SOX17 in open-access papers (continued):
Sharing a sentence is not in itself a finding about the gene and the disease.
non-small cell lung carcinoma (9 papers, 2019 to 2025). A group of at least three distinct histological types of lung cancer, including non-small cell squamous cell carcinoma, adenocarcinoma, and large cell carcinoma. "In another study, miR-200a is shown to induce proliferation and metastasis of non-small cell lung cancer (NSCLC) cells by targeting SOX17." (PMID 41271627, 2025). "Prospective biomarker studies have shown elevated DNA methylation markers CDO1 and SOX17 in the urine of patients with non-small-cell lung cancer (NSCLC)." (PMID 36591441, 2022). "Furthermore, SOX17 has been reported to be highly methylated in non-small cell lung cancer which correlates with the survival time of patients with this disease." (PMID 33833773, 2021). "The high frequency of SOX17 methylation in 50% of non-small-cell lung cancers and nearly 90% of esophageal squamous cancers strongly supports this possibility and is consistent with the known role of the aberrant activation of Wnt signaling during tumorigenesis for multiple cancer types." (PMID 31405379, 2019). "High-frequency methylation profiles have been reported for several cancer-specific genes, including SOX17, TAC1, HOXA7, CDO1, HOXA9, and ZFP42, in both preoperative plasma and sputum samples from lymph node-negative stage I and IIA non-small cell lung cancer (NSCLC) patients." (PMID 37840147, 2023).
hepatocellular carcinoma (8 papers, 2012 to 2023). A malignant tumor that arises from hepatocytes. "We also examined Sox17 gene expression in human HepG2 hepatoma cell line, which was in keeping with the reports that showed Sox17 gene expression in tumor cells including testicular germ cell tumors and all yolk sac tumors." (PMID 25013644, 2012). "Moreover, TNS4 expression was significantly increased in hepatocellular carcinoma and intrahepatic cholangiocarcinoma and was positively feedback-regulated by KRAS and SOX17 to stimulate migration and proliferation." (PMID 37328854, 2023).
ovarian carcinoma (8 papers, 2016 to 2026). A malignant neoplasm originating from the surface ovarian epithelium. "Another study demonstrated that PAX8 and SOX17 facilitated the secretion of angiogenic factors by ovarian cancer cells." (PMID 37856473, 2023). "We were unable to identify mutations in EMSY, BRIP, BARD1, and FOXM1 CNV in high-grade ovarian carcinoma as well as PTEN loss in clear cell carcinoma, LRPB1 loss and SOX17 amplification in uterine serous carcinoma." (PMID 36010253, 2022). "So the expressional profiles and relevance of SOX17 in ovarian cancer remains to be further validated." (PMID 33135729, 2020). "In ovarian cancer, the transcription factor PAX8 has been found to interact with SOX17 to promote angiogenesis, a crucial process for tumor growth and metastasis." (PMID 38981872, 2024). "In addition to PAX8, COPA complemented with pan-cancer analysis prioritized eight other lineage-restricted outliers (CDH6, CLDN16, FGF18, FOLR1, SLC34A2, SOX17, SPON1, WNT7A) displaying largely confined gene expression in ovarian cancer cell lines and tumor specimens." (PMID 31050342, 2019).
endothelial dysfunction (7 papers, 2023 to 2025). In vascular diseases, endothelial dysfunction is a systemic pathological state of the endothelium (the inner lining of blood vessels) and can be broadly defined as an imbalance between vasodilating and vasoconstricting substances produced by (or acting on) the endothelium. "SOX17‐associated exosomes, therefore, work well in endothelial dysfunction mostly through the combined utilization of miR‐224‐5p and miR‐361‐3p." (PMID 36919784, 2023). "SOX17 expression is maintained in a restricted fashion in the adult endothelium, but increases in response to inflammatory or hypoxic signaling and deficiencies in expression appear to increase the likelihood of endothelial dysfunction and subsequent PAH." (PMID 38028440, 2023). "Genetic risk variants upstream of the SOX17 promoter impair transcription factor binding, leading to reduced SOX17 expression in human PAECs (HPAECs) and contributing to endothelial dysfunction in PAH." (PMID 40066229, 2025). "We further detected the expression of SOX17 in HPAECs under multiple conditions that induce endothelial dysfunction." (PMID 36919784, 2023). "In this study, we confirmed that the PAECs‐derived exosomes improve endothelial dysfunction of pulmonary arteries induced by multiple factors in an autocrine manner and that SOX17 is a critical gene in maintaining endothelial function through this process." (PMID 36919784, 2023). "Sox17, an essential factor controlling endothelial and hematopoietic cell lineages, also plays an important role in regulating endothelial cell function and can be upregulated in response to endothelial dysfunction." (PMID 39253968, 2024). "Thereby, dysregulation in SOX17 expression or activity can contribute to endothelial dysfunction, which eventually may contribute to the development or progression of PAH." (PMID 37895315, 2023). "Indeed, insights are emerging into the pathophysiology of functional SOX17 loss in PAH and studies suggest that initial endothelial dysfunction may be a precursor for remodeling." (PMID 41034322, 2025). "Mechanistic studies uncovered that SOX17 promoted transcription and release of miR‐224‐5p and miR‐361‐3p, thereby targeting NR4A3 and PCSK9 to improve endothelial dysfunction." (PMID 36919784, 2023). "Thus, SOX17 loss may be a generalizable condition not unique to HPH, which may be closely related to endothelial dysfunction and vascular dyshomeostasis in IPH and other forms of PH." (PMID 36919784, 2023).
esophageal cancer (7 papers, 2016 to 2024). A primary or metastatic malignant neoplasm involving the esophagus. "SOX17 methylation is also associated with a history of alcohol consumption in esophageal cancer patients." (PMID 34488905, 2021). "For example, inhibition of Sox17 in esophageal cancer activated Wnt Signaling40, and upregulation of Sox17 inhibited canonical Wnt signaling in gut endoderm." (PMID 32371929, 2020). "Furthermore, the methylation levels of SOX17 (a Wnt signaling suppressor) increase along with the progression of esophageal cancer." (PMID 34488905, 2021). "Interestingly, the expression of CDH1 may be activated by SOX17, as suggested in esophageal cancer cells." (PMID 38675711, 2024). "Overexpressed SOX17 can then silence the tumor promoter GREB1, thereby reducing the proliferation and invasion of esophageal cancer cells and exerting anti-tumor efficacy in vitro." (PMID 37829341, 2023). "Re-expression of SOX17 via exposing 5-aza-2′-deoxycytidine attenuates TCF/beta-catenin-dependent transcription and proliferation of esophageal cancer cell lines." (PMID 34488905, 2021).
prostate carcinoma (7 papers, 2019 to 2025). A carcinoma that arises from epithelial cells of the prostate gland. "SOX17 up-regulation was associated with bone metastases in both prostate cancer (P = 0.014) and CRPC (P = 0.036) tissues." (PMID 33791203, 2021). "This study investigated the expression of SOX17, Notch receptors 1–4 in prostate cancer and CRPC tissue samples, and enzalutamide-resistant LNCaP cells (Enza-R)." (PMID 33791203, 2021). "In addition, SOX17 is also highly expressed in prostate cancer." (PMID 38675711, 2024). "The expression of SOX17 in CRPC tissues (64%, 21/33) was significantly higher than in prostate cancer tissues (42%, 15/36)." (PMID 33791203, 2021).
germ cell tumor (6 papers, 2009 to 2023). A benign or malignant, gonadal or extragonadal neoplasm that originates from germ cells. "Proteins were closely linked to proteins such as SOX-2, SOX-17, NANOG, or OCT3/4, which all have been described to play crucial roles in pluripotency and differentiation of germ cells and germ cell tumors." (PMID 31565104, 2019). "Moreover, we confirmed that LTR5_Hs were preferentially bound by KLF4, NANOG, POU5F1, and TFAP2C in naïve ESCs, by TFAP2C in PGCLCs, and by SOX17 in a germ cell tumor cell line using publicly available ChIP-Seq datasets." (PMID 35551519, 2022). "TCam-2 has elevated H3K4me3 and H3K27ac for SOX17 and low H3K4me3 and H3K27ac for SOX2 whereas NCCIT, an EC cell line derived from a mediastinal germ cell tumor, has elevated H3K4me3 and H3K27ac for SOX2 and low H3K4me2 and H3K27ac for SOX17." (PMID 36835562, 2023).
intracranial aneurysms (6 papers, 2015 to 2024). "In animal models, endothelial-specific SOX17 loss of function has been shown to result in impaired endothelial integrity, proliferation, paracrine regulation and increased development of intracranial aneurysms in response to hypertensive stress." (PMID 38028440, 2023). "SOX17 has also been associated with intracranial aneurysms in genome-wide association studies, and endothelial-specific Sox17 deficiency was subsequently shown to induce intracranial aneurysm pathology in an angiotensin II infusion mouse model." (PMID 30029678, 2018). "Less mechanistically defined, but of greater public health significance, is the positive correlation in multiple genome-wide association studies of non-coding single nucleotide polymorphisms at the Sox17 locus with intracranial aneurysms." (PMID 26630461, 2015). "Meanwhile, human genomic analysis has shown that the Sox17 site is one of the hot spots closely associated with intracranial aneurysms and that deficiency of Sox17 leads to the formation of hereditary-related intracranial aneurysms induced by high blood pressure." (PMID 37659973, 2024). "Interestingly, single nucleotide polymorphisms in the SOX17 gene have been associated with increased risk of intracranial aneurysm development in humans." (PMID 38028440, 2023). "SOX17 has been identified as a risk locus for intracranial aneurysms and SOX17 deficiency, which affects EC regeneration, may predispose to stress-induced intracranial aneurysms in hypertensive mice." (PMID 30984768, 2019). "The genetic ablation of Sox17 plus hypertension induced by AngII can lead to an increased incidence of intracranial aneurysms had tested in the previous animal experiments." (PMID 37659973, 2024). "It has also been reported that SOX17 is associated with intracranial aneurysms in genome-wide association studies, while the endothelial-specific knockout of Sox17 induced intracranial aneurysms." (PMID 37623346, 2023). "For example, SOX17 expression was diminished in intracranial aneurysms of adults undergoing microsurgical clipping, whereas it was highly expressed in intracranial arteries from controls." (PMID 38028440, 2023). "Our study revealed a previously unknown role of Sox17 in maintaining the function of vascular endothelial cells and demonstrated its impact on intracranial aneurysms." (PMID 37659973, 2024). "Loss of Sox17 function appears to disrupt cell to cell adhesion via decreased VE-cadherin expression—a possible explanation for both intracranial aneurysm development and non-functional vascular networks with decreased Sox17 function." (PMID 38028440, 2023).
lung adenocarcinoma (6 papers, 2021 to 2026). A carcinoma that arises from the lung and is characterized by the presence of malignant glandular epithelial cells. "Furthermore, SOX7 and SOX17 are notably associated with prognosis in lung adenocarcinoma." (PMID 41268614, 2026). "For example, SOX17 is downregulated in lung adenocarcinoma, and its upregulation suppresses NSCLC cell proliferation, suggesting a potential tumor-suppressive function." (PMID 41268614, 2026). "We aimed to elucidate SOX17 expression in cancer cells and the tumor microenvironment of lung adenocarcinoma." (PMID 39385307, 2024). "In the present study, we examined SOX17 expression in whole‐tissue specimens of 83 lung adenocarcinomas by immunohistochemistry." (PMID 39385307, 2024). "SOX17 immunoreactivity was minimal in lung adenocarcinoma cells, except in five non‐mucinous adenocarcinomas in situ." (PMID 39385307, 2024). "SOX17 was also expressed in cultured A549 lung adenocarcinoma cells, which is widely used as a model of malignant alveolar type II epithelial cells." (PMID 39385307, 2024). "Our findings indicate that SOX17 might play a pleiotropic role in lung adenocarcinoma in cancer cells and stromal niches." (PMID 39385307, 2024). "In a recent genome-scale CRISPR screen, LKB1 was identified as a master regulator of chromatin accessibility in lung adenocarcinomas, and the loss of LKB1 activated SOX17 in metastasis and in a metastatic-like subpopulation of cancer cells within primary tumors." (PMID 36497409, 2022). "Cao and colleagues found that UPF1 may inhibit TGF-β signaling by decreased expression of Smad2/3, MIXL1 and SOX17 in lung adenocarcinoma." (PMID 34922601, 2021).
yolk sac tumor (6 papers, 2010 to 2026). A non-seminomatous malignant germ cell tumor composed of primitive germ cells. "Intriguingly, SOX17 and BAMBI, implicated in yolk sac tumours, were increased in TCam-2 cells by both activin A and BMP4 exposure at 48 h." (PMID 37048077, 2023).
esophageal squamous cell carcinoma (5 papers, 2022 to 2024). Esophageal squamous cell carcinoma (ESCC) is a type of esophageal carcinoma (EC) that can affect any part of the esophagus, but is usually located in the upper or middle third. "Research indicates that the disulfidptosis-related genes CD96 and SOX17 could potentially act as independent prognostic factors in patients with esophageal squamous cell carcinoma (ESCC)." (PMID 38685115, 2024). "This study aimed to explore the relationships between the sex-determining region on Y (SRY) box transcription factor 17 (SOX17), Cyclin D1, vascular endothelial cadherin (VE-cadherin), and vasculogenic mimicry (VM) in the occurrence and development of esophageal squamous cell carcinoma (ESCC)." (PMID 36072972, 2022).
glioma (5 papers, 2012 to 2023). A benign or malignant brain and spinal cord tumor that arises from glial cells (astrocytes, oligodendrocytes, ependymal cells). "In one study, SOX17 was found to promote high-grade glioma by increasing vascular endothelial growth factor (VEGF) mediated vascular abnormality." (PMID 36604653, 2023). "The precise role of SOX17 in human glioma tumor cells, or specifically oligodendroglioma tumor cells, has not yet been evaluated." (PMID 26337424, 2016). "More recently, Holmberg and colleagues showed that high grade gliomas coexpress pluripotency transcription factors Oct4, Sox2, Nanog and Klf4 together with mesodermal Brachyury and endodermal Sox17 transcription factors." (PMID 22276221, 2012). "The methylation of SFRP1, SFRP2, PPP2R2B, DKK1, SOX17, and DACH1 was analyzed in 64 glioma samples using methylation-specific polymerase chain reaction (MSP)." (PMID 26337424, 2016). "Beside the genes, which were described earlier as possible targets of epigenetic silencing in gliomas (SFRP1, SFRP2, DKK1), the methylation of PPP2R2B, SOX17, and DACH1 was also assessed." (PMID 26337424, 2016).
teratoma (5 papers, 2010 to 2023). A non-seminomatous germ cell tumor characterized by the presence of various tissues which correspond to the different germinal layers (endoderm, mesoderm, and ectoderm). "The transcriptional analysis of teratoma tissues also showed the expression of genes of all three germ layers: the endoderm (SOX7, and SOX17), mesoderm (BRACHYURY, and MIXL1), and ectoderm (PAX6, and TUJ1)." (PMID 31888235, 2019). "We did find that the expression of Pax6 and Sox17 (except in GATA6) was lower than ES-EB, even though all of the selected iPSC lines in our study can generate teratoma, a gold standard of pluripotency." (PMID 22529890, 2012).
thyroid cancer (5 papers, 2016 to 2025). "In thyroid cancer, IL-22 induces miR-595 expression, which in turn downregulates Sox17 expression, thereby enhancing the migration and invasion of thyroid cancer." (PMID 32655554, 2020). "The relationship of the Sox gene family to the Wnt/β-catenin pathway was specifically shown when Sox17 expression was inhibited by hypermethylation of the promoter region, resulting in activation of Wnt signaling in human thyroid cancer." (PMID 26871472, 2016). "For instance, the regulation of thyroid cancer cell migration and invasion by TRIM30 involves targeting SOX17 for K48‐linked polyubiquitination, while E3 ligase E6‐AP affects SOX9 expression through ubiquitin‐mediated degradation, influencing cartilage development." (PMID 40918640, 2025). "Indeed, Ubiquitination of Sox17 has been reported in thyroid cancer." (PMID 38478109, 2024).
adenoma (4 papers, 2013 to 2024). A neoplasm arising from the epithelium. "To investigate the relation between methylation of SFRP2, WIF-1, DKK3 and SOX17 and the anatomical location of the adenoma, we divided all the adenomas into left- and right-sided adenomas." (PMID 24350795, 2013). "Methylation of SFRP2, WIF-1, DKK3 and SOX17 was significantly higher in carcinomas as well as both types of adenomas compared to normal colorectal mucosa." (PMID 24350795, 2013). "We discovered widespread hypermethylation of the Wnt antagonists SFRP1, SFRP2, SFRP5, DKK2, WIF1 and SOX17 in the transition from normal to adenoma with only the Wnt antagonists SFRP1, SFRP2, DKK2 and WIF1 showing further significant increase in methylation from adenoma to carcinoma." (PMID 25432628, 2014). "The present study focussed on promoter methylation of four known Wnt-pathway antagonists (SFRP2, WIF-1, DKK3 and SOX17), in polypoid and nonpolypoid adenomas, and its possible association with other molecular events that can play a role in Wnt-pathway activation." (PMID 24350795, 2013). "Consistent with this, Apc-mutant adenomas induced by CRISPR or Cre showed clear and abundant nuclear Sox17 staining in intestinal lesions." (PMID 28695896, 2017). "For APC methylation as well as for chromosome 5q loss, no relation was found with the promoter methylation results for SFRP2, WIF-1, DKK3 and SOX17 when combining both adenomas types or in nonpolypoid adenomas or polypoid adenomas, separately." (PMID 24350795, 2013).
biliary atresia (4 papers, 2016 to 2025). A rare, biliary tract disease characterized by progressive obliterative cholangiopathy of the intra- and extrahepatic bile ducts, occurring in the embryonic/ perinatal period, leading to severe and persistent neonatal jaundice and acholic stool. "Sox17 haploinsufficiency leads to gallbladder hypoplasia and causes biliary atresia with hepatic damage in the peripheral part of the liver." (PMID 39726108, 2025). "Sox17 is known to exhibit haploinsufficiency in bile duct formation, which results in biliary atresia and hepatitis in C57BL/6 background mice." (PMID 27053385, 2016). "The consequence is a congenital biliary atresia in extrahepatic ducts of Sox17+/− C57BL/6 embryos." (PMID 35887185, 2022).
breast tumors (4 papers, 2016 to 2021). "Moreover we have recently shown that SOX17 promoter is highly methylated in primary breast tumours, in CTCs isolated both from patients with early and metastatic breast cancer, and in corresponding ctDNA samples." (PMID 29069768, 2017).
cholangiocarcinoma (4 papers, 2018 to 2025). A carcinoma that arises from the intrahepatic biliary tree (intrahepatic cholangiocarcinoma) or from the junction, or adjacent to the junction, of the right and left hepatic ducts (hilar cholangiocarcinoma). "In support of this idea, SOX17 regulates cholangiocyte differentiation and functions as a tumor suppressor in cholangiocarcinoma." (PMID 39745200, 2025). "SRY-Box 17 (SOX17) regulates the phenotype of normal human cholangiocytes acting as a tumor suppressor in cholangiocarcinoma, occurring its downregulation through DNA methylation." (PMID 30237481, 2018).